CD44 (CD44 molecule (IN blood group))
Diseases named in the same sentence as CD44 in open-access papers (continued):
Sharing a sentence is not in itself a finding about the gene and the disease.
cancer (continued). "Therefore, the present study compared the expression profiles of the four cancer invasion-related genes in the CD44+ stem-like cells and their non-stem-like counterparts." (PMID 23833643, 2013). "The mutual expression of highly tumorgenic and metastatic-related genes, such as CD44, integrin α2β1, CD146, EGFR, and Flt-4, by epithelial- and mesenchymal-like cells indicates that cancer-stromal interactions of both types of cells may occur through common signaling pathways." (PMID 22330345, 2012). "Therefore, we envisage a combination of CD133 and CD44 as a more reliable characterization of stem-like character, consistent with a notable report proposing CD133+ CD44+ cells isolated from Huh7 as bona fide cancer progenitor cells." (PMID 22439738, 2012). "Indeed, CD44+/ALDH+ cells isolated from HNSCC exhibit increased radioresistance and reversal of this phenotype by a STAT3 signalling blocker restored radiosensitivity of cancer cells." (PMID 22333601, 2012). "CD44, CD49f, CD271, CD138 are basal cell markers, and some could be detected in the cancer cells." (PMID 21605402, 2011). "We have detected aberrant methylation in five cancer-related CpGIs, that is estrogen receptor-α [ESR1 (+244bp)], O6-methylguanine-DNA methyltransferase [MGMT (-463bp)], Wilms' Tumor-1 [WT-1 (-146bp)], Breast Cancer 2 [BRCA2 (+138bp)] and Hermen Antigen [CD44 (+28bp)]." (PMID 22011321, 2011). "CD44 has been shown to anchor the proteolytically-active form of MMP-9 to the cell surface while the constitutive expression of either the transcription factor ID-1 or the receptor DDR1 has been reported to increase the activity of MMP-9 and the invasiveness of human cancer cells." (PMID 21283680, 2011). "The differential expression of hypoxia marker HIF-1α in CD44+CD24-/low tumors is in accordance with the current knowledge regarding relationship between microenvironmental factor such as hypoxia or anoxia states with maintenance and propagation of cancer stem cells." (PMID 21824412, 2011). "We demonstrated that CD44+ but not CD44− cells from selective cancer cell lines could be expanded and serially propagated in vitro and in vivo." (PMID 21124918, 2010). "Thus, expression of other transporters, or different drug resistance mechanisms, such as aldehyde dehydrogenase, which was over-expressed in both CD44+/CD24- and CD133+ cell types, may be operational in Brca1 cancer stem cells." (PMID 18241344, 2008). "MEK or p38 but not JNK reduced CD44 total RNA by 40%–65% in cancer and benign cells." (PMID 18793421, 2008). "The absence of the CD44 surface marker was unexpected but could reflect the true phenotype of the cancer stem cell, the CD24low/- CD44+ profile reflecting the phenotype of progenitor cells." (PMID 18541018, 2008). "However, Sox9-positive cells did not exhibit increased levels of the cancer stemness marker CD44." (PMID 39518936, 2024). "Furthermore, CD44-high cells could form lung metastases in immunodeficient mice, in contrast to CD44-low cells, which failed to exhibit a similar metastatic proliferation of cancer cells." (PMID 37189717, 2023). "Therefore, cell findings of EpCam+ and CD44+ CRC did not overlap which may not exclude the likelihood of the presence of cancer stem phenotype at a very small fraction, yet suggesting that the CD44+ CRC identified in the donors are different to CTC and CEB." (PMID 36100762, 2023). "In addition, studies have shown that CD44 can stabilize the SLC7A11 subunit on the cell membrane, promote the growth of CRC cells, and increase SLC7A11-dependent protection from reactive oxygen species (ROS), thus enabling cancer cells to escape from oxidative damage." (PMID 36672372, 2023). "PDL1 could also be a biomarker for this cancer, although it is not as effective as CD44." (PMID 37173926, 2023).
cancer (continued). "This hypothesis was tested in which a siRNA against CD44 was combined with paclitaxel and loaded in a dendrimer functionalized with the luteinizing hormone-releasing hormone (LHRH) peptide to confer the nanosystem targeting properties to cancer cells of gynecologic origin." (PMID 37287910, 2023). "However, there is no universal set of biomarkers that can be used to recognize and isolate CSCs CD44 and CD133 transmembrane glycoproteins are widely putative as general CSC markers in many types of tumors, and are involved in normal cellular processes and also in cancer development." (PMID 38328436, 2023). "The subsequent CD44 conjugation and cancer cell targeting with fluorescein loaded liposomes displayed a strong signal of the liposomal uptake further validating that neither the DSPE-PEG-MAL molecules nor the CD44 antibodies were lost as micelles or during filtration." (PMID 35323794, 2022). "However, this general rule may not apply to all cancer cell lines because a cancer cell line was initially established from one or only a few cells, and the broad expression of CD44 or other markers cannot disqualify them as PCSC markers simplistically." (PMID 36358865, 2022). "CD44+CD24−GRP78+ head and neck cancer cells exhibit strong capabilities of tumorigenesis, chemo-radioresistance, and invasion, fitting the hypothesis that cancer stem cells possess the properties of unlimited self-renewal and enhanced motility across different niches." (PMID 35883497, 2022). "Notably, a transmembrane ubiquitin ligase family member MARCH8 has been associated with lysosome degradation of both CD44 and CD81 in fibroblast cells and/or TNBC cells, suggesting CD44 and CD81 might follow similar fates of protein degradation or recycling in both cancer cells and other cells." (PMID 36193887, 2022). "The signal for LY6E and CD44 was opposite to their expression pattern in mouse at both the single-cell and metacell levels, suggesting that their expression in DCs subtypes may not be conserved between human and mouse or across cancer types." (PMID 35963997, 2022). "Therefore, GBM cancer cells could shift cancer cells from the proliferation state to hibernation state through autophagy as a survival function, followed by enhancement of CD133/CD44/Nestin/SOX2 as GSC markers to support the stochastic model." (PMID 34069945, 2021). "Since xenograft mice models do not fully reflect the nature of the human immune system, one major reason could be that CD44 is indeed expressed by many healthy cells, including T cells, fibroblasts and macrophages, and its targeting using CAR T cells might mediate toxicity in cancer patients." (PMID 34944493, 2021). "However, the mechanism of CD44 clustering in cancer progression is not well illustrated." (PMID 33292278, 2020). "To determine whether physciosporin affects the expression of cancer stemness markers in CRC cells, we monitored the protein expression level of aldehyde dehydrogenase-1 (ALDH1), cluster of differentiation 133 (CD133), CD44, Lgr5, and Musashi-1 (Msi-1) in CSC221 cells." (PMID 31795147, 2019). "Moreover, this is not the first time CD44 and clinical prognosis of cancer patients is observed." (PMID 28421110, 2017). "Furthermore, the decrease in cancer stem cells surface markers phenotype (CD90, CD44, CD133, CD13 and CD24) observed in combined DATP and XAV939 was no more than that observed by either individual treatment, suggesting that Notch and Wnt/β-Catenin may have cross-talk between each other." (PMID 26735577, 2016).
cancer (continued). "In summary, although the high expression of CD44 in CSCs, and other cell types render CD44 as an attractive molecule for a targeted vaccine therapy, the use of CD44 vaccination has been confined to pre-clinical studies in very limited number of cancer and non-cancer models." (PMID 25954275, 2015). "Additionally, CD44+ cancer cells rather than CD133+ cells have an increased tumorigenicity." (PMID 19583834, 2009). "In the present study, ex vivo experiments demonstrated that mEp-NIR-PIT effectively eradicated cancer cells while sparing T cells and dendritic cells (DCs) in the TME, unlike CD44-NIR-PIT, which reduced these immune cell populations." (PMID 40792441, 2025). "CD44, a new ligand for CD6, is also expressed on cancer cells as well as many non-malignant cell types." (PMID 39996744, 2025). "Although not covered in the current investigation, cancer stem cell markers including CD133, CD44, DLK1, and Notch1 as well as the β-catenin/p-GSK3β signaling pathway were significantly down-regulated, and the self-renewal capacity of CSCs was suppressed." (PMID 39000345, 2024). "Mice with hepatocytes lacking CD44 showed reduced development of HCC, suggesting CD44 is not only cancer stem cells marker but also a functional molecule that contributes to HCC development." (PMID 36930869, 2023). "MDA-MB-231 cancer cells were cultured with or without JQ1 for 24 h, and the CD44+/CD24− and ALDH-expressing subpopulations were determined." (PMID 37924094, 2023). "Circulating CD44+/CD45− rare cells from healthy, noncancer- and cancer-afflicted donors were enriched by CD45 depletion and analyzed by immuno-fluorescence microscopy." (PMID 36100762, 2023). "The data on the expression of stem cell markers CD44, CD24, and ALDH1A1 in the breast tissue of cancer-free women is very limited and no previous studies have explored the agreement between pathologist and computational assessments of these markers." (PMID 36590957, 2022). "We found that the percentage of NCAMhiCD44lo/– tumors, defined with over 50% of cancer cells highly expressing NCAM and with low or no CD44 expression, increased with malignant progression and metastasis." (PMID 35967587, 2022). "Unfortunately, another study showed the opposite effect depending on cell characteristics, including induction of CD44, OCT-4 and NANOG on HNSC cancer stem cells but decreased proliferation of nonstem cancer cells." (PMID 35327549, 2022). "In radioresistant cancer stem cells (CSCs) during tumor regrowth, areas including cancer cells positive for CSC markers, such as aldehyde dehydrogenase, CD44, and CD133, did not significantly increase in irradiated tumors compared to non-irradiated ones." (PMID 35130955, 2022). "CD15s expression was compared between mesenchymal-like cancer stem cells (CSC, CD44+CD24−), epithelial cells without CD44 (CD44−CD24+ and CD44−CD24−), and CD44+CD24+ cells that exhibit mesenchymal and epithelial features." (PMID 34206154, 2021). "We found that cancer cells overexpress epithelial-to-mesenchymal transition markers TWIST1 and SNAI2, as well as stem-like marker CD44 (but not CD133, SOX2 and/or NANOG)." (PMID 33531664, 2021). "CD44 and ALDH1 are well-known cancer stemness drivers; however, their expression has not been studied in detail." (PMID 34163000, 2021). "Although previous studies showed that K-RAS and CD44 played significant roles in various cancer, there is a lack of study of K-RAS and CD44 functional role in radiation-treated GBM." (PMID 34681583, 2021). "CD15s expression was compared among mesenchymal-like cancer stem cells (CSC, CD44+CD24−), epithelial cells without CD44 (CD44−CD24+ and CD44−CD24−), and CD44+CD24+ cells that exhibit mesenchymal and epithelial features." (PMID 34206154, 2021).
cancer (continued). "The percentages of CD44+ and/or CD133+ cells in the hiPSC population were virtually non-existent compared with their respective parental cancer cell populations." (PMID 32795421, 2020). "We further compared the mRNA level of cancer stemness markers in AZD4547-treated (2 μM) vs. non-treated control L3.6 cells and found that CD24, CD44, and CD133, were dramatically down-regulated upon AZD4547 treatment." (PMID 32457900, 2020). "Of interest, the ability of MMP-9 to favor the spread of tumor cells can also be helped by nonintegrin receptors such as CD44 and CD151, which are coexpressed with MMP-9 by highly invasive cancer cells." (PMID 32630531, 2020). "As the cells of origin, MSC-derived EVs were positive for CD29, CD44, CD105, and negative for hematopoietic, epithelial, and cancer stem cell markers." (PMID 30915084, 2019). "The expression of cancer stem cell surface markers, such as CD133, CD44, or EpCam, was not influenced by salinomycin treatment." (PMID 30763370, 2019). "The proliferative DSCs were Double-positive for two cancer stem cell markers, CD133 and CD166, but negative for CD44, which is commonly used to isolate stem cell populations in many tissues." (PMID 31804471, 2019). "It was observed that the CD24- CD44+ CSCs were also positive for expression of CD133 and TF, whereas non-CSC CD24- cancer cells were negative for express of CD133 (not shown)." (PMID 27903969, 2017). "CSCs were isolated based on triple marker-positive status (CD44+/CD133+/EpCAM+); and isolated non-CSC bulk cancer cells expressed none of these cell surface protein markers; i.e., triple marker-negative (CD44/CD133/EpCAM)." (PMID 28281569, 2017). "BC cells with phenotypes CD44+/CD24−/ALDH+ and CD44+/CD133+/ALDH+ showed increased tumorigenicity and metastases when compared with the non-stem cancer cells." (PMID 28445439, 2017). "We characterized expression of Syndecan-1 and the CSC marker CD44, Notch-1 & -3 and EGFR in carcinoma tissues of triple negative IBC (n = 13) and non-IBC (n = 17) patients using qPCR and immunohistochemistry." (PMID 28270211, 2017). "In this study, we examined the expression of Syndecan-1 and its correlation with the CSC marker CD44, Notch-1 & -3 and EGFR expression in carcinoma tissues of triple negative IBC and non-IBC patients." (PMID 28270211, 2017). "Of note, YAP knockdown led to a decrease in the size and number (by 2-fold) of spheres and cancer stem cell markers ALDH1A3, CD133 and Lgr5, with no change in CD44." (PMID 27527859, 2016). "Hyaluronan, a non-sulfated glycosaminoglycan, has two major receptors, CD44 and RHAMM, which mediate its roles in inflammation and cancer." (PMID 26869928, 2016). "Especially, specific receptors for HA such as CD44 and RHAMM are frequently overexpressed in cancer cells rather than normal cells." (PMID 26163139, 2015). "On the other hand, stem cell markers such as OCT4, SOX2, NANOG and GATA4 and cancer stem cell (CSC)–like markers including ALDH1A1, CD44 and CD133 were not upregulated." (PMID 25875914, 2015). "In recent studies ALDH was identified as the CSC marker for various types of cancer including ovarian, breast, lung and prostate cancer, CD44+CD24− for breast and ovarian cancer, CD133 for non-small cell lung, liver and lung cancer." (PMID 25351876, 2015). "Breast CICs often express high levels of CD44 and lower levels of CD24 (CD44↑CD24↓) than the non-CIC population which is referred frequently to as the bulk cancer." (PMID 25051360, 2014). "This suggests that CD44 is not constituitively expressed in invadopodia but may be recruited there only upon a sufficiently high concentration of its agonist, hyaluronan, which can be concentrated at the invasive front of tumors and may be important in cancer stem cell-niche interactions." (PMID 24086451, 2013).
cancer (continued). "Overall, the significant over-expression of stem cell markers SOX2, OCT4, SOX9 and CD44 suggests that the cells present in spherical aggregates are CSC-like whereas the non-spherogenic, adherent layer of cells are non-CSC cancer cells." (PMID 24423398, 2013). "Unlike the CD molecules, ALDH1 is a recently identified cancer stem cell marker which has greater specificity than CD133 and CD44 for colorectal CSCs." (PMID 23599758, 2013). "To characterize the CSC-like cells (cells present in the sphere-like aggregates), we compared the expression levels of CD44, OCT-4, SOX2 and SOX9 between CSC-like (spherogenic) and non-CSC (non-spherogenic) UM1 cancer cells with Western blotting." (PMID 24423398, 2013). "Most slides from cancer-free tissue lacked expression of CCND1, CD44, CDH1, EGFR, ERBB2, KIT, keratins, NOTCH1, PAK1, PTGS2, SNAI1, and VIM but showed staining of MUC1, HIF1A, NKX2-1, SFTPC, and STAT3, which were also found in AdCa." (PMID 23028920, 2012). "The expression of CD44 was assessed initially at transcript level by mining the IST database that includes tissue samples from normal non-neoplastic tissues, malignant neoplasms and other diseases." (PMID 22242150, 2012). "Coincidentally, the majority of SW480 cells, the non-metastatic precursor cells of SW620, have the CD44+CD133− surface marker, therefore, CD44+ and CD133− are not the only determinants of CSCs for these cancer cells." (PMID 22895640, 2012). "In contrast, the ArLa contained less than 1% CD44+/CD24−/low cells and were thus defined as the non-initiating (non-CIC) cancer cell type." (PMID 21079774, 2010). "Interestingly, CD44 has also been identified as a cancer stem cell (CSC) marker in PCa; CD44-positive cells are more proliferative, clonogenic, tumorigenic, and metastatic than isogenic CD44-negative cells." (PMID 40141159, 2025). "TAMR and ADR cells showed a significant increase in CSC population, which was revealed by the sphere-forming ability and relative number of CSCs that were identified with antibodies specific to cancer stem cell surface markers, CD24 negative and CD44 positive (CD24-/CD44+)." (PMID 38664825, 2024). "Similarly, lipid rafts (LRs) are significantly enriched in cancer stem cells (CSCs) compared to non-stem cancer cells, and key CSC markers, such as CD24, CD44, and CD133, are located within these lipid rafts, underscoring their pivotal role in CSCs." (PMID 38396837, 2024). "Moreover, the high content of CD44 and lack of CD24 were confirmed, which is related to cancer-like stem cell (CSC) features." (PMID 39408826, 2024). "Additionally, western blot and RT-qPCR analysis confirmed the positive regulation of CBX7 and IGF-1R on cancer stem cell markers CD133 and CD44, rescuing the negative influence of FOXC1 knockdown on these markers." (PMID 38413558, 2024). "Taking into account that CD44 and CD133 have substantial expression in untreated cells that cannot all be CSCs, their elevation in RTP state is supposed not so much the feature of cancer stemness than a critical factor supporting survival of RTP cells." (PMID 36658726, 2023). "CD44, a non-kinase receptor, is a CSC marker in many cancer types." (PMID 35846884, 2022). "These CD44 positive cells were absent in the blood-alone control lacking MDA-MB-231 cells, confirming the results from the CSS Analyzer II where the CCT2 stain was used to detect spiked cancer cells." (PMID 35749519, 2022). "Also, CD44 has been found to be correlated with unfavorable PFS and cancer-specific survival in non-muscle-invasive papillary upper tract urothelial carcinoma." (PMID 33303029, 2020).